RNU6-1129P (RNA, U6 small nuclear 1129, pseudogene)
Gene: Small nuclear RNA gene on chromosome 3 (86,235,321 to 86,235,424, forward strand). Ensembl gene ENSG00000251773.
Homologues: Orthologues: chimpanzee U6 (98% identical), macaque U6 (90% identical), pig U6 (84% identical), mouse Gm55916 (70% identical). Paralogues in human: RNU6-259P (86% identical), RNU6-589P (86% identical), RNU6-1060P (84% identical), RNU6-116P (84% identical), RNU6-19P (84% identical), RNU6-637P (84% identical), RNU6-1303P (83% identical), RNU6-166P (83% identical), RNU6-26P (83% identical), RNU6-348P (83% identical), RNU6-41P (83% identical), RNU6-44P (83% identical), and 1289 more.